IL1B (interleukin 1 beta)
Diseases named in the same sentence as IL1B in open-access papers (continued):
Sharing a sentence is not in itself a finding about the gene and the disease.
Sepsis (continued). "Some hypotheses suggest that sepsis is associated with an early overwhelming innate immune response, characterized by dysregulation of the overproduction of cytokines (TNF-α, IL-1β, IL-6, IL-8)." (PMID 34017259, 2021). "Subsequent studies found that Z-VAD-FMK could significantly reduce IL-1β release in patients with LPS-and S. aureus-induced sepsis by inhibiting caspase activity." (PMID 34305952, 2021). "Indeed, IL‐1β expression and inflammasome formation has been shown to impair myocardial function in cardiomyopathy and sepsis settings." (PMID 34435466, 2021). "Oral administration of chemically stable MIC-1 (80 mg/kg) significantly reduced the expression of inflammatory markers (Tnf-α, Ifn-α, IL-1β, IL-6) in the liver, kidney, spleen, and colon and decreased spleen weight in the lipopolysaccharide (LPS)-induced sepsis / acute inflammation model in mice." (PMID 33793581, 2021). "It is also tempting to speculate that IL‐1β‐induced cardiac atrophy facilitates diastolic cardiac function, which in turn occurs at later time points during sepsis." (PMID 34472725, 2021). "DG has been reported to effectively inhibit bacterial endotoxin–induced HMGB1 release in vitro and help mice defend against lethal endotoxemia and CLP-induced sepsis, and inhibit pro-inflammatory mediators IL-1β and TNF-α, thereby protecting LPS-induced endotoxic shock in rabbits." (PMID 34938184, 2021). "This suggested that DEX could reduce the levels of TNF-α, IL-1β, and IL-10 after sepsis induction at the early stage." (PMID 33981237, 2021). "The level of IL-1β within the brain is elevated by peripheral administration of endotoxins, simulating sepsis, suggesting that systemic infection may exacerbate already present brain inflammatory responses in Alzheimer’s disease." (PMID 33723589, 2021). "According to Maher’s findings (2014), the CSTB-deficient mice were significantly more sensitive to the lethal LPS-induced sepsis and could secrete higher amounts of pro-inflammatory cytokines IL-1β and IL-18." (PMID 33926569, 2021). "IL-1β concentration is significantly increased in sepsis in the peripheral and CNS." (PMID 34062710, 2021). "During sepsis, the cardiodepressant and inflammatory cytokine IL‐1β rapidly increases." (PMID 34472725, 2021). "Pro-inflammatory cytokine IL-1β is downregulated by similar epigenetic regulation during sepsis." (PMID 35052507, 2021). "Intermittent elevation of TNF-α and IL-1β in inflammatory response and sepsis has been reported." (PMID 34870560, 2021). "Notably, LPS increased neutrophil expression of CD274 (PD-L1), which is consistent with other stimulants of sepsis, such as IL-1β, HMGβ1, G-CSF and IL-4." (PMID 33549126, 2021). "In sepsis patients, JKAP level negatively associated with TNF-α, IL-1β, and IL-17 expressions." (PMID 33083958, 2021). "Many studies have highlighted the role of Nlrp3 inflammasome/IL-1β pathway in promoting CVD and the link between inflammation and CVD is further highlighted by the link between sepsis survivor and higher risk of having a heart attack or stroke." (PMID 34395445, 2021). "Partial depletion of Tregs elevated IL-17A, IL-1β, and IL-6 production and decreased IL-10 levels, leading to lower bacterial load and attenuation of lung injury in secondary P. aeruginosa infection after sepsis." (PMID 34222495, 2021). "Additionally, an influence of IL-1β secretion by skeletal muscle cells in pathological conditions such as sepsis has been proposed, where it mediates and promotes the development of muscle atrophy." (PMID 34638553, 2021). "Because NLRP3/IL‐1β pathway inhibition attenuates cardiac atrophy and cardiomyopathy in sepsis, it could be useful to prevent septic cardiomyopathy." (PMID 34472725, 2021). "Finally, rats from sepsis groups exhibited higher IL-1β mRNA expression than controls, confirming that the CLP protocol induced a metabolic disorder associated with an upregulation of proinflammatory cytokines." (PMID 33825987, 2021).
Sepsis (continued). "Results confirmed that inhibition of miR-378a-3p expression could significantly reduce the level of TNF-α, IL-1β, IL-6 in the serum of sepsis rats, and thus improved the inflammatory response induced by sepsis." (PMID 34565302, 2021). "Therefore, these previous studies support our findings that sepsis reduced basal synaptic transmission, concomitant with a remarkable increase in IL-1β in SAMP8 and that IL-1ra administration prevented these effects." (PMID 33643027, 2021). "TNFα, IL-6, IFNγ, IL-1β and IL-10 were measured in brain of mice 6 h after induction of sepsis." (PMID 33608025, 2021). "In contrast, IL-1β serum levels are only slightly increased during sepsis." (PMID 34017259, 2021). "In a study that collected serial samples from patients meeting sepsis-3 criteria until discharge, differences in cytokine measurements on Day 1 of sepsis were seen, where IL-1β, IL-10, IL-6, and IL-8 levels were among six cytokines found to be significantly elevated compared to controls." (PMID 33820537, 2021). "However, if IL‐1β directly mediated cardiomyopathy and cardiac atrophy in sepsis needs to be proven." (PMID 34472725, 2021). "In accordance with the expected results, we observed a significant increase in the expression levels of pyroptosis-related markers in the liver of CD38-deficient septicemia mice, such as NLRP3, cleaved caspase-1, IL-1β, and IL-18, accompanied by the increase in cleaved caspase-3." (PMID 33860064, 2021). "Blocking the activity of IL-1β by IL-1 receptor reduced the mortality of patients with sepsis." (PMID 35096304, 2021). "Liang et al19 demonstrated that PIP could protect macrophages from pyroptosis and reduce IL‐1β release, thereby becoming a potential therapeutic agent against bacteria sepsis." (PMID 33219747, 2021). "Tumor necrosis factor-α (TNF-α), interleukin-1β (IL-1β), and IL-6 are three major inflammatory cytokines that actively participate in mediating the development of organ injury (e.g., that of the liver) induced by endotoxemia and sepsis." (PMID 34065201, 2021). "Next, we found that Pellino1 protein could induced the protein expression of Pellino1, TRAF6 and NF-κB and increased the levels of TNF-α, IL-6, IL-1β and IL-18 in mice of sepsis." (PMID 33632252, 2021). "Furthermore, PBMCs with the sepsis-associated risk allele 29940G in NLRP3 exhibited significantly enhanced expression of NLRP3 and release of IL-1β and TNF-α compared to those with the C allele under LPS stimulation." (PMID 34172780, 2021). "Consequently, we measured the production of IL-6, TNF-α and IL-1β in sepsis patients and healthy controls and in PBMCs under in vitro LPS stimulation to investigate the effect of the NLRP3 29940 G>C variation on the production of these related cytokines." (PMID 34172780, 2021). "Here, we investigated the role of NLRP3/IL‐1β in sepsis‐induced cardiomyopathy and cardiac atrophy." (PMID 34472725, 2021). "During sepsis, neutrophil numbers in the peripheral blood are increased by a massive release of mature and immature neutrophils from the bone marrow as a result of the signaling from specific pro-inflammatory cytokines (such as TNFα, IL-1β)." (PMID 34966382, 2021). "In addition, the beneficial effects of monoclonal antibody-based anti-TNF-α, anti-IL-1β, or anti-IL-6 therapy individually on sepsis have previously been reported." (PMID 34065201, 2021). "IL-1β expression was also decreased during sepsis (GSE49755)." (PMID 34439987, 2021). "As sepsis-induced disruption of tissue homeostasis leads to aberrant regulation of both anti- and pro-inflammatory cytokines (CKs), we sought to determine the expression of IL-1β, IL-6, IL-10, TGF-β1, and TNFα, the main drivers of tissue inflammation." (PMID 33803290, 2021). "During sepsis, pathogen-associated molecular patterns and damage-associated molecular patterns activate TLRs, which then trigger inflammation by stimulating the production and release of pro-inflammatory cytokines, specifically TNF-α and IL-1β." (PMID 34177611, 2021).
Sepsis (continued). "Our data also implicate that IL‐1β contributes to diastolic cardiac dysfunction during sepsis." (PMID 34472725, 2021). "Therefore, it is reasonable that it was the postsynaptic mechanisms that were mainly affected in SAMR1 and normal adult mice, in which hippocampal IL-1β levels are slightly elevated during sepsis." (PMID 33643027, 2021). "In an in vivo sepsis study, RvD1 decreased IL-6, TNFα, IL-1β and IFNγ levels significantly." (PMID 33815391, 2021). "Indeed, IL-1b and IL-10 levels were higher in patients who deteriorated compared to those who improved only in the group of patients with sepsis with sufficient predictive value (AUROCs 0.71 and 0.72, respectively)." (PMID 33917002, 2021). "During sepsis, IL‐1β serum levels increased in WT mice, which was attenuated in KO mice." (PMID 34472725, 2021). "In our previous study, we also indicated that eight functional polymorphisms (IL1B-1470, IL1B-511, IL1B-31, IL4-589, IL6-572, IL8-251, IL10-819, and TNFA-308) could be combined together to predict the risk of sepsis and organ dysfunction after trauma." (PMID 33281864, 2020). "Twenty-four hours after CLP, there were a significant increase in proinflammatory cytokines (TNF-α, IL-1β, and IL-6) in serum and an elevated death rate in rats, while the surviving rats developed septic syndrome; this demonstrated that our sepsis model was successfully established." (PMID 32765805, 2020). "In the presence of obesity, sepsis resulted in increased IL-1β and IL-6 levels in PLF." (PMID 33223959, 2020). "However, sepsis increased the gene expression of IL-1β in all the dietary groups (+61, +189 and +102%, respectively) compared to the sham-operated animals of the DEF, ALA and EPA groups." (PMID 32365668, 2020). "The Sepsis-G group even had higher ALT and IL-1β concentrations than the sham and Sepsis-C groups." (PMID 32295272, 2020). "TRPM7 expression and levels of TNF-α, IL-6 and IL-1β are increased in the serum of patients with sepsis diagnosis and those patients with sepsis and a high expression of TRPM7 have a decreased survival rate in comparison to patients with a low expression of TRPM7." (PMID 33291725, 2020). "In vivo and in vitro experiments also found that asiatic acid reduced the levels of inflammatory factors (IL-1β ↓, IL-6 ↓) by affecting the Notch signaling pathway, weakened liver and kidney damage, and improved the survival rate in the experimental sepsis mice model." (PMID 33013406, 2020). "Endothelial pyroptosis is a vital mechanism of vascular endothelial injury in sepsis, and this process leads to the release of a plethora of pro-inflammatory cytokines, such as IL-1β and LDH, and destroys the endothelium barrier, eventually leading to septic shock and multiple organ failure." (PMID 32795289, 2020). "IL-6 production is stimulated by TNFα, and IL-1β, and may contribute to the systemic inflammation in critical illness and sepsis." (PMID 33105809, 2020). "IL-1β-induced multiple organ damage in sepsis has also been reported." (PMID 33324236, 2020). "Intraperitoneal administration of 5-MTP to LPS-induced sepsis model results in suppression of macrophage activation and cytokine expression accompanied by reduction of serum cytokines (IL-6, IL-1β, TNFα and IFNγ) and chemokines (CXCL-1, MCP-1, Rantes and Eotaxin)." (PMID 32635910, 2020). "In our study, LPS was able to promote IL-6 and IL-1β production in rat sepsis model." (PMID 29984678, 2020). "Furthermore, it downregulated the transcriptions of proinflammatory cytokine IL-6, TNF-α, and Il-1β and upregulated IL-10 transcription in the liver of sepsis mice." (PMID 32457606, 2020). "Indeed, the intravenous infusion of riboflavin into the sepsis mice alleviated the plasma level of pro-inflammatory mediators, such as TNFα, IL-1β, IL-6, INFγ, MCP1, and NO5,6." (PMID 33154451, 2020). "Therefore, TNFα, IL-1β, and IL-6 are currently considered to be markers of the early phase of sepsis." (PMID 32793229, 2020).
Sepsis (continued). "Moreover, previous studies demonstrated that CLP-induced sepsis significantly increased IL-1β and NLRP 3 levels in the lung and kidney." (PMID 33381582, 2020). "The levels of diaphragmatic TNF-α, IL-1β, and IL-6 were increased significantly in rats in the sepsis group compared to rats in the sham group 24 h after surgery (P < 0.01), while TNF-α, IL-1β, and IL-6 concentrations at 24 h after CLP were reduced after NRG-1β treatment (P < 0.01)." (PMID 32765805, 2020). "Furthermore, simvastatin and cerivastatin improved survival rate and reduced serum TNF-α and IL-1β in a murine model of sepsis." (PMID 33110395, 2020). "The activation of NLRP3 inflammasome has been proved to contribute to the inflammatory response of sepsis-induced AKI, which causes an impaired kidney morphology, increased renal tubular cell apoptosis, and NLRP3-dependent proinflammatory cytokine (i.e., IL-1β and IL-18) production." (PMID 32454788, 2020). "IL-1β concentrations in lung and spleen tissue mirror the delayed increase of this cytokine in plasma, whereas cerebral tissue levels of this cytokine remain low with a peak mean concentration of 33 pg/mg protein after 5.5 h of sepsis duration." (PMID 33072121, 2020). "In addition, TQ acted by reducing sepsis-induced increase in the expression of inflammatory signals including that of IL-1-β, IL-6, and TNF-α in the kidney tissue." (PMID 32626733, 2020). "Because TNF-α and IL-1β activate endothelial cells during sepsis, we investigated whether other cytokines could similarly induce proinflammatory cytokine and PAI-1 production in endothelial cells." (PMID 32826331, 2020). "Similarly, we found an increased TNF-α, IL-1β, and IL-6 levels in the serum, the hippocampus, and the frontal cortex at day 1 and day 10 after sepsis onset." (PMID 32457609, 2020). "Injury to intestinal epithelial barriers and microbial translocation can lead to a systemic response that mimics some aspects of sepsis and unveils a massive release of inflammatory cytokines, such as IL-1β, that increases neutrophil and macrophage recruitment and activation." (PMID 30622186, 2019). "Finally, MRS suppressed the activation of the NLRP3/Caspase-1/IL-1β inflammasome signaling pathway to alleviate the tissue and cell damage induced by sepsis." (PMID 30779706, 2019). "Importantly, IL-1β levels of MLN DCs were markedly elevated by sepsis; in fact, IL-1β expression of septic MLN DCs overwhelmed that of septic SP DCs." (PMID 31323786, 2019). "TNF-α and IL-1β are prototype pro-inflammatory cytokines involved in the pathogenesis of sepsis." (PMID 31818040, 2019). "However, the peripheral blood mononuclear cells (collected within 24 h of late onset sepsis) from the extremely preterm group secreted higher levels of IL-1β, than the very preterm neonates." (PMID 30873043, 2019). "Thus, it can be deduced that the inflammatory action of MLN DCs in sepsis, via IL-1β, is dependent upon mediation via TLR4 and/or HMGB1." (PMID 31323786, 2019). "In fact, pro-inflammatory cytokines play an important role during sepsis, specially IL-1β." (PMID 31536570, 2019). "In accordance with organ dysfunction in the FtHfl/fl mice, 24 h after CLP surgery, there was a significant increase in the levels of cytokines that have been implicated in the pathogenesis of sepsis, including the pro-inflammatory cytokines, TNF-α, IFN-γ, IL-6, IL-12, CXCL1, IL-1β, and IL-2." (PMID 30804939, 2019). "This increase in expression was reduced by MRS/MRM treatment, indicating that methane could inhibit the NLRP3/caspase-1/IL-1β signaling pathway to decrease pyroptosis offering a protective effect during sepsis." (PMID 30779706, 2019). "Deficient autophagy was associated with increased NLRP3 inflammasome assembly and culminated caspase-1 activation as observed in sepsis, enabling enhanced cleavage of pro-IL-1β and pro-IL-18 into their biologically active forms IL-1β and IL-18 in DSS-treated UVRAGFS mice colons." (PMID 31831743, 2019).
Sepsis (continued). "This neuroprotective effect of clenbuterol in the memory impairment induced by sepsis was accompanied by polarizing microglia toward an anti-inflammatory phenotype, reducing proinflammatory cytokines including IL-1β and TNF-α, and reversing synaptic abnormalities." (PMID 31354429, 2019). "Notably, early clenbuterol treatment alleviated sepsis-induced cognitive deficits by polarizing microglia toward an anti-inflammatory phenotype, reducing proinflammatory cytokines including IL-1β, TNF-α, and up-regulating CREB/BDNF, PSD95, and GluN2B." (PMID 31354429, 2019). "During sepsis, macrophages are activated by various stimuli, such as gram-negative bacteria and LPS, resulting in transcriptional upregulation of inflammatory genes, including inducible nitric oxide synthase (iNOS), IL-1β, and TNF-α." (PMID 31847346, 2019). "Cytokines, such as TNF-α and IL-1β, are extensively produced at the early stage of sepsis." (PMID 31671563, 2019). "Based on our results, it is tempting to speculate that the IL-1β upregulated by mucosal DCs may engage in proliferating CD4 T cells during sepsis." (PMID 31323786, 2019). "The inhibition of IL-1β protects against LPS-induced sepsis." (PMID 31333903, 2019). "Additionally, there was reduced IL-1β and IL-18 release at 2, 6, 18, and 24 h after the induction of sepsis." (PMID 30873043, 2019). "Additionally, it has been found that serum levels of IL-1β and TNFα are only 45%–50% lower in healthy patients than those hospitalized with sepsis." (PMID 30897777, 2019). "Furthermore, mucosal DCs in sepsis preferentially expressed IL-1β messaging, which has been reported to directly expand CD4 T cells." (PMID 31323786, 2019). "Unlike TNF-α, whose synthesis and secretion are inflammasome-independent, production of IL-1β and IL-18, which requires inflammasome-dependent caspase-1 activation, was more abundant in the serum of Dox-induced iUVRAGFS mice than littermate control in sepsis." (PMID 31831743, 2019). "During sepsis, the homeostasis between pro-inflammatory and anti-inflammatory cytokines is disrupted, resulting in the release of inflammatory factors, such as IL-6, IL-1β, and TNF-α." (PMID 31555126, 2019). "Thus, in the present study, the inhibition of let-7a-5p resulted in significantly increased concentrations of TNF-α, IL-1β, IL-6, and iNOS and decreased hepatic function in mice with sepsis." (PMID 29599918, 2018). "The TNF-α, IL-1β, and IL-6 concentrations in patients with sepsis were markedly greater compared to those in the controls, and the levels also increased with the development of sepsis." (PMID 30268141, 2018). "Sepsis is one of the most common causes of ALI, with LPS being the most important biological mediator as they induce the secretion of inflammatory cytokines, such as TNF-α, IL-1β, and IL-6 in response to bacterial toxins." (PMID 30083155, 2018). "We found that, in a previous study, exogenous Cit alleviated the release of proinflammatory cytokines (TNF-α, IL-1β, and IL-6) in early sepsis and increased the release of late-stage anti-inflammatory cytokines (IL-4 and IL-10) to alleviate the inflammatory response of septic rats." (PMID 30498752, 2018). "In our study, we found that AA decreased levels of interleukin-1β (IL-1β), IL-6, alanine aminotransferase and blood urea nitrogen in serum; attenuated liver, lung and kidney damage; and improved the survival among mice with experimental sepsis." (PMID 29599924, 2018). "Among the inflammatory cytokines, tumor necrosis factor-α (TNF-α), interferon-γ (IFN-γ), and interleukin-1β (IL-1β) are detected in the blood of patients with sepsis and induce septic shock-like conditions when administered in animals in vivo, suggesting their critical pathogenic roles in sepsis." (PMID 29928698, 2018).